FAM169A (family with sequence similarity 169 member A)
Synonyms: SLAP75; KIAA0888; SLAP
Tractability: Antibody: UniProt places it where antibodies can reach, with high confidence. PROTAC: ubiquitination databases record sites on it; its protein half-life has been measured.
Gene: Protein-coding gene on chromosome 5 (74,777,574 to 74,867,022, reverse strand). Ensembl gene ENSG00000198780.
Subcellular location: Nucleus envelope; Nucleus inner membrane
Subcellular location (Human Protein Atlas): Cytosol; Nuclear membrane
Pathways (Reactome):
Signal Transduction: RHOF GTPase cycle
Gene Ontology:
Molecular function: protein binding
Cellular component: nuclear membrane; nuclear envelope; nuclear inner membrane
Genetic constraint (gnomAD): Loss-of-function variants: 11 observed, 42.17 expected, observed/expected ratio (o/e) 0.26, 90% interval 0.16 to 0.43. The upper end of that interval is the gene's LOEUF score, 0.43, which puts it in group 1 of 6, group 1 being the genes least tolerant of losing a copy. Missense variants: 487 observed, 562.11 expected, observed/expected ratio (o/e) 0.87, 90% interval 0.8 to 0.93. Synonymous variants: 186 observed, 198.67 expected, observed/expected ratio (o/e) 0.94, 90% interval 0.83 to 1.06.
Homologues: Orthologues: chimpanzee FAM169A (99% identical), macaque FAM169A (97% identical), dog FAM169A (90% identical), pig FAM169A (90% identical), rabbit FAM169A (90% identical), mouse Fam169a (80% identical), rat Fam169a (78% identical), guinea pig FAM169A (75% identical), tropical clawed frog fam169a (45% identical), zebrafish fam169ab (26% identical), zebrafish fam169aa (23% identical).
Diseases named in the same sentence as FAM169A in open-access papers:
FAM169A is named in the same sentence as 2 diseases in open-access papers, as found by Europe PMC text mining. Sharing a sentence is not in itself a finding about the gene and the disease.
FAM169A shares sentences with these, for which no sentence is quoted: intervertebral disc degeneration (1 paper); neurodevelopmental disorder (1).